SNAI3 (snail family transcriptional repressor 3)
Description:
Seems to inhibit myoblast differentiation. Transcriptional repressor of E-box-dependent transactivation of downstream myogenic bHLHs genes. Binds preferentially to the canonical E-box sequences 5'-CAGGTG-3' and 5'-CACCTG-3' (By similarity).
Synonyms: ZNF293; SMUC; Zfp293; SNAIL3
Tractability: No criterion of Open Targets' tractability assessment is met for any kind of drug.
Gene: Protein-coding gene on chromosome 16 (88,677,688 to 88,686,507, reverse strand). Ensembl gene ENSG00000185669.
Subcellular location: Nucleus
Subcellular location (Human Protein Atlas): Nucleoplasm
Gene Ontology:
Molecular function: sequence-specific double-stranded DNA binding; DNA-binding transcription factor activity, RNA polymerase II-specific; RNA polymerase II cis-regulatory region sequence-specific DNA binding; copper ion binding; DNA-binding transcription factor activity; DNA-binding transcription repressor activity, RNA polymerase II-specific; RNA polymerase II transcription regulatory region sequence-specific DNA binding
Biological process: regulation of DNA-templated transcription; negative regulation of transcription by RNA polymerase II
Cellular component: nucleus; transcription regulator complex
Genetic constraint (gnomAD): Loss-of-function variants: 19 observed, 15.56 expected, observed/expected ratio (o/e) 1.22, 90% interval 0.85 to 1.75. The upper end of that interval is the gene's LOEUF score, 1.75, which puts it in group 6 of 6, group 1 being the genes least tolerant of losing a copy. Missense variants: 354 observed, 312.32 expected, observed/expected ratio (o/e) 1.13, 90% interval 1.04 to 1.24. Synonymous variants: 160 observed, 139.46 expected, observed/expected ratio (o/e) 1.15, 90% interval 1.01 to 1.31.
Homologues: Orthologues: chimpanzee SNAI3 (98% identical), macaque SNAI3 (93% identical), dog SNAI3 (78% identical), mouse Snai3 (73% identical), guinea pig SNAI3 (70% identical), pig SNAI3 (68% identical), rat Snai3 (65% identical), Drosophila melanogaster wor (45% identical), tropical clawed frog snai3 (43% identical). Paralogues in human: SNAI2 (47% identical), SNAI1 (40% identical), SCRT1 (36% identical), SCRT2 (36% identical), ZNF410 (24% identical), PRDM1 (24% identical), HIC1 (23% identical), ZBTB16 (23% identical), ZNF76 (22% identical), MTF1 (21% identical), PRDM10 (21% identical), ZBTB7C (21% identical), and 24 more.
Diseases named in the same sentence as SNAI3 in open-access papers:
SNAI3 is named in the same sentence as 20 diseases in open-access papers, as found by Europe PMC text mining. Sharing a sentence is not in itself a finding about the gene and the disease. The quoted sentences say what the papers report.
lung carcinoma (4 papers, 2014 to 2023). "Consistent with the results of bioinformatics analysis, the expression levels of SETDB2 and SNAI3 were higher in BEAS-2B than in lung cancer cell lines." (PMID 37197420, 2023). "The wound healing assay showed that depletion of SETDB2 or SNAI3 promoted the migration of lung cancer cells." (PMID 37197420, 2023). "The deletions of both SETDB2 and SNAI3 were found to promote proliferation, invasion, and stemness in lung cancer cells." (PMID 37197420, 2023). "In addition, the roles of SETDB2, SNAI3, SCML4, ZNF540, and ETV1 were validated in multiple datasets and human lung cancer cell lines." (PMID 37197420, 2023).
breast carcinoma (3 papers, 2014 to 2023). "Whereas SNAI3 expression was found to be associated with good prognosis in breast cancer." (PMID 37197420, 2023). "At the same time, we also further analyzed the expression levels of SNAI2 and SNAI3 in breast cancer." (PMID 35898399, 2022). "SNAI3 has been less well studied, but we found that it is positively correlated with good prognosis in breast cancer." (PMID 35898399, 2022). "The SNAI3 gene also appeared to be expressed in several human breast cancer cell lines, although the induction level was much lower (FC>5 in 36.3%, n = 11), while SNAI2 expression remained unchanged." (PMID 24638100, 2014). "Obviously, the lower level of SNAI3 transcript observed in breast cancer cell lines than in tumors suggests that part of the signal observed in patient samples is attributable to the stromal compartment." (PMID 24638100, 2014). "However, the SNAI3 expression had an opposite effect on the prognosis of breast cancer patients." (PMID 35898399, 2022). "In breast cancer, SNAI1 and SNAI2 expression was high, whereas SNAI3 expression was low." (PMID 35898399, 2022).
breast tumor (2 papers, 2014). "With exception of SNAI3, all the up-regulated genes are known to be involved in breast tumor malignancy and include the transcription factor FOXC2, PDGFRB and members of the WNT family, whose products are known to sustain the metastatic process of breast tumors." (PMID 24962430, 2014). "In conclusion, both SNAI1 and SNAI3 gene expressions are induced in primary breast tumors compared to normal mammary epithelial cells, suggesting that likewise SNAIL1, SNAIL3 may also contribute to breast tumorigenesis." (PMID 24638100, 2014).
gastric cancer (2 papers, 2020 to 2021). A primary or metastatic malignant neoplasm involving the stomach. "DAXX overexpression inhibited the growth of gastric cancer through downregulating snail family transcriptional repressor 3 (SNAI3), a key inducer of EMT, by recruiting HDAC-1 into the nucleus." (PMID 35087762, 2021). "In this study, we showed for the first time that DAXX inhibits the development of gastric cancer by inhibiting SNAI3- mediated EMT." (PMID 32203224, 2020). "The mechanisms by which DAXX induces downregulation of SNAI3 in gastric cancer cells are not clear." (PMID 32203224, 2020).
germ cell tumor (2 papers, 2021 to 2024). A benign or malignant, gonadal or extragonadal neoplasm that originates from germ cells. "Human SNAI3 (Snail3) mRNA was expressed in skin melanoma, lung squamous cell carcinoma, and germ cell tumors." (PMID 38398019, 2024).
B cell deficiency (1 paper, 2013). A broad classification of disorders where circulating numbers of B lymphocytes are decreased or ineffective. "Of these, the Snai2-/- Snai3+/- animals show a greater B cell deficiency than the Snai2+/- Snai3-/- animals." (PMID 23874916, 2013).
colorectal cancer (1 paper, 2020). A primary or metastatic malignant neoplasm that affects the colon or rectum. "According to previous reports, FOXD4 induces the progression of colorectal cancer by regulating the SNAI3/CDH1 axis and can be used as a marker of colorectal cancer." (PMID 32509568, 2020).
invasive breast carcinoma (1 paper, 2022). A carcinoma that infiltrates the breast parenchyma. "In contrast, for SNAI3, deep deletion was the most frequent alteration, with a percentage of 2.4% in epithelial ovarian carcinoma and of 2.49% in invasive breast carcinoma." (PMID 35898399, 2022).
lipid metabolism disorder (1 paper, 2024). "Compared with the Control group, the mRNA expression of Srebf2, Scap, Hmgcr, Soat1, Npc1, Snai3, Twist1, Itgav, Vegfc, and Tgfbr1 has higher expression in model group, indicating that there is lipid metabolism disorder in model mice." (PMID 38724499, 2024).
prostate carcinoma (1 paper, 2023). A carcinoma that arises from epithelial cells of the prostate gland. "For example, in induced pluripotent stem cells (iPSC) and prostate cancer cells, mesenchymal genes, such as ZEB1, ZEB2, CDH2, TWIST and SNAI1/2, are enriched with EZH2 binding, but not epithelial genes such as CDH1 or SNAI3." (PMID 37175580, 2023).
Testicular atrophy (1 paper, 2013). Wasting (atrophy) of the testicle (the male gonad) manifested by a decrease in size and potentially by a loss of fertility. "In contrast, single germline deletions of either Snai2 or Snai3 are viable although Snai2 deficient males are described as having decreased fertility due to testicular atrophy." (PMID 23874916, 2013).
tumor (12 papers, 2012 to 2026). "The finding is consistent with our results and corroborates that SNAI3 can inhibit tumor onset and development." (PMID 35898399, 2022). "Some TFs are associated with multiple PTPs, such as several tumor metastasis regulators (ZEB1, SNAI3, and SMAD2)." (PMID 36341348, 2022). "Our data suggested that the signal flow from PEDF to SNAI3 and its downstream molecules may control the extravasation and reorganization of tumor in specific target organs." (PMID 35174090, 2022). "The function of SNAI3 in tumor progression is unknown, but it has been reported that it may be related to survival." (PMID 35898399, 2022). "SNAI1 and SNAI3 induction did not associate with a specific tumor subtype and were not correlated one to each other." (PMID 24638100, 2014). "To investigate the role of CBPRS in the tumour microenvironment (TME) at the single-cell transcriptome level, we analysed the expression patterns of SOD1, MUC2, FKBP4, LOXL2, GPC1 and SNAI3 in different cell types." (PMID 38577594, 2024). "Expression level of FCGR1A, although not correlated with VIM or CDH1, had r = 0.31 and r = 0.42 with SNAI1 and SNAI3 respectively, suggesting it may be co-expressed with these EMT drivers in some tumours." (PMID 27876705, 2016). "We also investigated some genes frequently associated with collective (DDR1, eIF4GI) and mesenchymal migration (Snai3), but found no significant expression difference between our tumor types." (PMID 22748014, 2012).
cancer (7 papers, 2012 to 2023). A tumor composed of atypical neoplastic, often pleomorphic cells that invade other tissues. "While the SNAI1 and SNAI2 genes are reported to be frequently reactivated in numerous carcinomas (breast, esophageal, colon, kidney), the status of the related SNAI3 gene has remained unclear." (PMID 24638100, 2014). "However, SNAI2 and SNAI3 expression were downregulated and upregulated, respectively, in primary cancer cells." (PMID 35898399, 2022). "Members of the SNAI family (Snail (SNAI1), Slug (SNAI2), and Smuc (SNAI3)) of transcriptional regulators trigger EMT, and are considered useful indicators of the malignancy of cancer." (PMID 33198344, 2020). "A strong increase in invasive capacity was also observed in cells over-expressing LTBR and YWHAE and to a lesser degree SNAI3 and GFI1, indicating that all these genes can drive EMT in more than one model system and have the potential to promote invasiveness of carcinomas." (PMID 27876705, 2016).
SNAI3 also shares sentences with these, for which no sentence is quoted: adenomyosis (1 paper); Atrophy (1); kidney cancer (1); lung adenocarcinoma (1); lung squamous cell carcinoma (1); skin melanoma (1); thyroid carcinoma (1).